ORMDL3 (ORMDL sphingolipid biosynthesis regulator 3)
Description:
Plays an essential role in the homeostatic regulation of sphingolipid de novo biosynthesis by modulating the activity of the serine palmitoyltransferase (SPT) in response to ceramide levels. When complexed to SPT, the binding of ceramides to its N-terminus stabilizes a conformation that block SPT substrate entry, hence preventing SPT catalytic activity. Through this mechanism, maintains ceramide levels at sufficient concentrations for the production of complex sphingolipids, but which prevents the accumulation of ceramides to levels that trigger apoptosis.
Tractability: Small molecule: a structure with a bound ligand is known. Antibody: its Gene Ontology location is reachable by antibodies, with high confidence; UniProt predicts a signal peptide or a membrane-spanning region. PROTAC: UniProt records ubiquitination sites on it; ubiquitination databases record sites on it; its protein half-life has been measured.
Gene: Protein-coding gene on chromosome 17 (39,921,037 to 39,929,328, reverse strand). Ensembl gene ENSG00000172057.
Subcellular location: Endoplasmic reticulum membrane
Subcellular location (Human Protein Atlas): Endoplasmic reticulum
Pathways (Reactome):
Immune System: Neutrophil degranulation
Metabolism: Sphingolipid de novo biosynthesis
Gene Ontology:
Molecular function: protein binding
Biological process: ceramide metabolic process; negative regulation of B cell apoptotic process; negative regulation of ceramide biosynthetic process; positive regulation of autophagy; positive regulation of protein localization to nucleus
Cellular component: endoplasmic reticulum; endoplasmic reticulum membrane; serine palmitoyltransferase complex; plasma membrane; secretory granule membrane; specific granule membrane; membrane
Genetic constraint (gnomAD): Loss-of-function variants: 6 observed, 12.98 expected, observed/expected ratio (o/e) 0.46, 90% interval 0.25 to 0.91. The upper end of that interval is the gene's LOEUF score, 0.91, which puts it in group 3 of 6, group 1 being the genes least tolerant of losing a copy. Missense variants: 159 observed, 216.21 expected, observed/expected ratio (o/e) 0.74, 90% interval 0.64 to 0.84. Synonymous variants: 99 observed, 90.42 expected, observed/expected ratio (o/e) 1.09, 90% interval 0.93 to 1.29.
Homologues: Orthologues: chimpanzee ORMDL3 (99% identical), macaque ORMDL3 (99% identical), dog ORMDL3 (99% identical), pig ORMDL3 (99% identical), guinea pig ORMDL3 (98% identical), rabbit ORMDL3 (98% identical), rat Ormdl3 (97% identical), mouse Ormdl3 (97% identical), zebrafish ormdl3 (92% identical), Drosophila melanogaster ORMDL (50% identical). Paralogues in human: ORMDL1 (84% identical), ORMDL2 (81% identical).
Diseases named in the same sentence as ORMDL3 in open-access papers:
ORMDL3 is named in the same sentence as 78 diseases in open-access papers, as found by Europe PMC text mining. Sharing a sentence is not in itself a finding about the gene and the disease. The quoted sentences say what the papers report.
asthma (221 papers, 2008 to 2026). "Initially identified through its genetic link to asthma susceptibility, ORMDL3 plays a key role in regulating sphingolipid metabolism by inhibiting Serine Palmitoyltransferase activity." (PMID 41884618, 2026). "Among genetic contributors, the orosomucoid-like 3 (ORMDL3) gene, a negative regulator of sphingolipid synthesis, has gained particular importance and has been significantly linked to the onset of asthma." (PMID 41939571, 2026). "In genetic analysis, genome-wide association studies (GWASs) show that the ORM (yeast)-like protein isoform 3 (ORMDL3) gene encoded in the 17q21 locus is probably associated with severity and exacerbations in asthma." (PMID 40001485, 2025). "When using the method proposed in the study to analyze the factors related to the onset of asthma, it was found that the indicator closely linked to this disease was the expression level of ORMDL3." (PMID 40161025, 2025). "We sought to clarify the association between variants in gasdermin B/orosomucoid-like 3 (GSDMB/ORMDL3) on 17q21 and exacerbations in type 2–low asthma." (PMID 40687950, 2025). "ORMDL3, a gene linked to asthma susceptibility, also influences macrophage function; transgenic mice overexpressing ORMDL3 show increased IgE levels and enhanced immune cell recruitment, including macrophages." (PMID 40076729, 2025). "These epigenetic mechanisms provide a potential explanation for the observed association between ORMDL3 risk alleles and RV-induced wheezing and early-onset asthma phenotypes." (PMID 40806756, 2025). "Another interesting example is the IKZF3/GSDMB/ORMDL3 GWAS locus, which is linked to many autoimmune diseases, including RA, asthma, systemic sclerosis (SSc), and others." (PMID 39930543, 2025). "Genetic variants in ORMDL3 are associated with sphingolipid synthesis and altered metabolism, which contribute to asthma." (PMID 40126553, 2025). "The rs7216389 polymorphism influences asthma in children by altering the expression of genes like ORMDL3 and gasdermin B (GSDMB), which are involved in immune regulation and airway inflammation." (PMID 39906448, 2025). "Studies in children also have demonstrated that polymorphism rs7216389 carriers exhibit high ORMDL3 gene expression in airway cells, predisposing them to ER stress and disturbed calcium signaling, which are connected to inflammation processes in asthma." (PMID 39906448, 2025). "For instance, individuals carrying the T/C genotype who are exposed to secondhand smoke show a heightened risk of asthma symptoms due to increased gene expression of ORMDL3, which is involved in airway remodeling and inflammation." (PMID 39906448, 2025). "An in vitro study using asthmatic mice revealed that histone hyperacetylation at the ORMDL3 gene is linked to asthma, and the resulting increase in ORMDL3 expression is associated with airway remodeling." (PMID 41008562, 2025). "If rs12936231 is not activated, then there is activation of the other CTCF-binding site (rs4065275) intronic to ORMDL3, thus favoring the expression of ORMDL3 and increased asthma risk." (PMID 38567749, 2024). "An association between elevated ORMDL3 protein levels and asthma has not only been observed in humans but also in experimental mice and even in Drosophila." (PMID 38715613, 2024). "Numerous genome-wide association studies have identified ORMDL3 as a gene associated with asthma susceptibility." (PMID 38699230, 2024). "Expression levels of ORMDL3 are associated with the development of inflammatory and autoimmune diseases including asthma, systemic lupus erythematosus, type 1 diabetes mellitus and others." (PMID 38715613, 2024). "The molecular mechanisms underlying ORMDL3’s pathologic functions in asthma are connected to its evolutionarily conserved role in the regulation of sphingolipid homeostasis." (PMID 38699230, 2024).
asthma (continued). "These polymorphisms were shown to perturb ORMDL3 gene expression, and risk variants associated with asthma had increased ORMDL3 expression contributing to risk of triggering childhood asthma." (PMID 38417794, 2024). "We obtained 24 iQTLs associated with this loop, all of them being significant nCD4 eQTLs of GSDMB and 21 of them (like the SNPs rs2305479, rs7216389) are nCD4 eQTLs for the asthma risk associated gene ORMDL3." (PMID 39289357, 2024). "Previous studies have shown that genetic variation affecting ORMDL3 expression is an important determinant of asthma susceptibility and predisposition to other autoimmune or inflammatory diseases." (PMID 39744015, 2024). "A case-control association study conducted in the Japanese population observed that ORMDL3/GSDMB is an important susceptibility gene for early-onset adult asthma." (PMID 38562155, 2024). "ORMDL3 has been implicated in a variety of disorders including asthma, inflammatory bowel disease, and obesity." (PMID 37124760, 2023). "The first genome-wide association study (GWAS) for asthma was published in 2007 and showed that genetic variants on chromosome 17q21.1 were associated in cis with transcript levels of ORMDL3." (PMID 37569643, 2023). "ORMDL3 gene has been associated with childhood-onset asthma and other inflammatory diseases in which mast cells play an important role." (PMID 37316542, 2023). "These and other asthma risk variants at 17q21 (rs4065275, rs12936231, rs7216389) increase ORMDL3 expression on CD4+ T cells, reducing interleukin-2 production." (PMID 37762787, 2023). "Genome-wide association studies (GWAS) have identified the orosomucoid-like 3 (ORMDL3) gene as that is responsible for childhood-onset asthma risk." (PMID 36430378, 2022). "who focused on mapping the effects of SNPs associated with childhood asthma and revealed the association of the ORMDL3 gene with susceptibility to asthma." (PMID 35693821, 2022). "Many studies have shown that ORMDL3 is associated with genetic susceptibility and the potential pathogenesis of asthma." (PMID 35972600, 2022). "Conversely, eQTL analysis has also been used to show a strong relationship between ORMDL3 transcription levels and multiple asthma-associated SNPs." (PMID 35693821, 2022). "For example, multiple studies have identified ORMDL3 as an asthma susceptibility gene with asthma risk." (PMID 36818476, 2022). "Gene expression commonly regulated in PTSD and severe asthma, included ORMDL3 a gene known to be associated with asthma risk and STX8, which is involved in TrkA signaling." (PMID 36206293, 2022). "Some genes were linked to specific asthma phenotypes, including ORMDL3/GSDMB/LRRC3C (17q21.1), which is linked with childhood asthma." (PMID 36294997, 2022). "Asthma-associated SNPs in this locus are related to levels of mRNA expression of ORMDL3 in lymphoblastic cell lines using eQTL mapping, which associates SNPs with gene expression." (PMID 35656293, 2022). "Numerous GWAS have identified ORMDL3 as a potential susceptibility gene for asthma and polymorphisms controlling ORMDL3 expression have been associated with both asthma occurrence and exacerbation." (PMID 36206293, 2022). "ORMDL3 is encoded by the ORMDL gene family which is strongly correlated with asthma in genome-wide association studies." (PMID 35316427, 2022). "Histone hyperacetylation of ORMDL3 is associated with asthma, and increased ORMDL3 expression is associated with airway remodeling and Ca2+ oscillations." (PMID 34566492, 2021). "In another study, the HAT loss resulted in the downregulation of the ORMDL3 gene, which is a childhood asthma gene." (PMID 33781317, 2021). "Previous genome-wide association studies showed that ORMDL3 is a risk factor of childhood-onset asthma and linked this disease with SNPs mapped in the 17q21 region, where the human ORMDL3 with other five coding genes resides." (PMID 34560079, 2021).
asthma (continued). "In particular, infections with human rhinovirus (HRV), the most common trigger for asthma exacerbations, are associated with a more than 10-fold increased odds ratio for childhood asthma in children who carry the asthma-associated ORMDL3 genotype." (PMID 35386967, 2021). "Gasdermin B (GSDMB) locus on chromosome 17q21 is associated with childhood-onset asthma in ethnically different populations In close proximity to GSDMB, ORMDL3 gene showed a highly reproducible association with childhood onset asthma at GWAS." (PMID 33925009, 2021). "Subsequent in vitro investigations silencing ORMDL3 reported attenuated pro-inflammatory responses and reduced ICAM1 expression, providing a potential mechanistic basis for ORMDL3 and RV susceptibility in asthma." (PMID 35386999, 2021). "The chromosomal region 17q21 harbors the human orosomucoid‐like 3 (ORMDL3) gene and has been linked to asthma and other inflammatory diseases." (PMID 34288557, 2021). "In contrast, the risk alleles implicated in asthma are linked to increased levels of the ORMDL3 gene transcript." (PMID 34560079, 2021). "Much attention has been focused on the regulation of SPT by ORMDL3, as single-nucleotide polymorphisms of ORMDL3 have been associated with asthma susceptibility, although its role in regulating sphingolipid levels has been controversial." (PMID 33939982, 2021). "Variants of the complex 17q21 region affecting GSDMB and ORMDL3 were previously found to be determinant for childhood asthma susceptibility and development of Rhinovirus-induced wheezing in preschool age." (PMID 33925009, 2021). "Identification of ORMDL3 as a major susceptibility locus by several genome‐wide association studies of human asthma patients suggests that this axis is likely to play an important role in this inflammatory disease." (PMID 34288557, 2021). "In some studies, ORMDL3, an ER transmembrane protein, has been heavily implicated in asthma related ER stress." (PMID 35386986, 2021). "Several studies reported that the asthma associated ORMDL3 (ORMDL Sphingolipid Biosynthesis Regulator 3) gene regulated the sphingolipid biosynthesis, and the altered sphingolipids modulate the T cells’ metabolism." (PMID 33967801, 2021). "Chromosome 17 ORMDL3 locus is now recognised as the major predisposing factor for childhood-onset asthma." (PMID 34001091, 2021). "For wheeze at month 18, we found significant associations of UMC only in the asthma risk strata of the single-nucleotide polymorphisms at the 17q21 locus related to ORMDL3 (rs8076131) and GSDMB (rs7216389 and rs2290400, all p-values for interaction < 0.001)." (PMID 33986744, 2021). "Subsequent studies demonstrated that ORMDL3/GSDML variants are associated with a high risk of asthma in diverse ethnic groups." (PMID 34946955, 2021). "We have previously shown an association between asthma and differential methylation of ORMDL3 from peripheral blood leukocytes in asthmatic children from the Swedish Search Study, and methylation levels at specific sites correlated with gene expression." (PMID 33971943, 2021). "In a genome-wide association study, the ORMDL3 (ORMDL sphingolipid biosynthesis regulator 3) gene was identified as having a strong association with asthma." (PMID 34122136, 2021). "ORM1-like 3 (ORMDL3), a gene located on chromosome 17q12-21, has been highly linked to childhood onset asthma in genetic association studies." (PMID 33661765, 2021). "GWAS studies showed ORMDL3 expression is increased with asthma risk alleles, suggesting SPT inhibition is relevant to asthma pathogenesis." (PMID 34931265, 2021). "In 2007, a genome-wide association study (GWAS) of asthma identified single nucleotide polymorphisms (SNPs) flanking ORMDL3 gene on chromosome 17 to be significantly associated with the disease." (PMID 34001091, 2021). "Meanwhile, consistent with the previous studies, the TT genotype of ORMDL3 (rs7216389) is associated with asthma exacerbation and the severity of asthma." (PMID 33031402, 2020).
asthma (continued). "This review has focused on the role of human CD4+ T cells in exacerbating asthma phenotypes in the context of 17q12–21 asthma risk SNPs associated with heightened ORMDL3 expression." (PMID 33424845, 2020). "Recent studies have linked childhood asthma to the orsomucoid-1-like protein 3 (ORMDL3) gene and the asthma susceptibility locus at 17q21." (PMID 33339279, 2020). "Single-nucleotide polymorphisms (SNPs) in chromosome 17q12-q21, where the human ORMDL3 gene resides, have been associated in genome-wide association studies with the childhood onset asthma and increased ORMDL3 mRNA levels." (PMID 33643282, 2020). "Lower sphingolipid synthesis is related to 17q21 variations, which are associated with asthma risk and higher ORMDL3 expression." (PMID 33339279, 2020). "Regarding the de novo synthetic pathway of sphingolipids, genome-wide association studies revealed that single nucleotide polymorphism (SNP) of oroscomucoid-like protein 3 (ORMDL3) at the 17q21 locus increased the risk of asthma." (PMID 33031402, 2020). "The TT genotype of ORMDL3 (rs7216389) has been reported to be associated with asthma exacerbation and the severity of asthma." (PMID 33031402, 2020). "The enzyme encoded by the ORMDL3 gene in the 17q21 region, which is the most replicated childhood asthma genetic locus, inhibits the first step in de novo sphingolipid synthesis." (PMID 32155960, 2020). "In the first genome wide association study for asthma published in 2007, it was reported that the ORMDL3/GSDMA locus at chromosome 17q12 was specifically associated with childhood onset asthma." (PMID 32603359, 2020). "The chromosome 17q21 locus that carries GSDMB and ORMDL3 harbors more than a dozen SNPs linked to asthma." (PMID 32500120, 2020). "In fact, early studies had revealed that SNPs associated with asthma co-regulate the expression of ORMDL3, GSDMB, and ZPBP2 in Latinos." (PMID 30805318, 2019). "The GSDMB/ORMDL3 locus on chromosome 17q21 is the most consistently replicated genetic region associated with asthma." (PMID 31001502, 2019). "One of the most well replicated genetic regions affecting asthma risk is the 17q12–21 locus, which includes ORMDL3 and GSDMB." (PMID 31443563, 2019). "Expression of the orosomucoid-like 3 (ORMDL3) gene has been genetically linked to pro-inflammatory diseases, such as asthma, Crohn’s disease, ulcerative colitis, and rheumatoid arthritis, suggesting ORMDL3 involvement in immune system function." (PMID 30897694, 2019). "Most susceptibility genes for complex lung diseases such as asthma have homologs in the fly, and it was possible to elucidate the functional role of the asthma susceptibility gene ORMDL3 using this approach." (PMID 30766617, 2019). "Increased orosomucoid-like 3 (ORMDL3) expression levels, due to single nucleotide polymorphisms (SNPs), have been associated with several inflammatory diseases, including asthma and inflammatory bowel diseases." (PMID 30897694, 2019). "Filaggrin deficiency is one of the top genome-wide genetic determinants of asthma, along with the variants found that regulate ORMDL3 expression." (PMID 30473631, 2018). "The asthma-associated gene ORMDL3 regulates endoplasmic reticulum stress, and respiratory viruses are closely associated with both development and exacerbations of asthma." (PMID 29966020, 2018). "The roles of CD48 as a costimulatory receptor of various immune responses, its involvement in allergen-induced airway inflammation, and its regulation in mice by ORMDL3 have strongly implicated CD48 association to human asthma." (PMID 30306094, 2018). "The ORMDL3 gene, which encodes a transmembrane protein of the ER, has been shown to be associated with asthma in several studies." (PMID 29966020, 2018). "Overexpression of ORMDL3 decreases T lymphocyte activation, and variants in ORMDL3 are associated with asthma and several other immune-mediated inflammatory diseases." (PMID 30323283, 2018).